ENSG00000284341 (novel transcript)
Gene: Protein-coding gene on chromosome 9 (136,977,518 to 136,985,435, forward strand). Ensembl gene ENSG00000284341.
Genetic constraint (gnomAD): Missense variants: 236 observed, 248.13 expected, observed/expected ratio (o/e) 0.95, 90% interval 0.85 to 1.06. Synonymous variants: 101 observed, 109.28 expected, observed/expected ratio (o/e) 0.92, 90% interval 0.79 to 1.09.